GJD3 (gap junction protein delta 3)
Description:
One gap junction consists of a cluster of closely packed pairs of transmembrane channels, the connexons, through which materials of low MW diffuse from one cell to a neighboring cell.
Synonyms: Cx31.9; GJA11; GJC1; Cx30.2
Tractability: Antibody: UniProt places it where antibodies can reach, with high confidence; its Gene Ontology location is reachable by antibodies, with high confidence; UniProt predicts a signal peptide or a membrane-spanning region.
Gene: Protein-coding gene on chromosome 17 (40,360,652 to 40,364,737, reverse strand). Ensembl gene ENSG00000183153.
Subcellular location: Cell membrane; Cell junction, gap junction
Pathways (Reactome):
Vesicle-mediated transport: Gap junction assembly
Gene Ontology:
Molecular function: protein binding; gap junction channel activity involved in AV node cell-bundle of His cell electrical coupling; gap junction channel activity involved in cardiac conduction electrical coupling; gap junction channel activity; monoatomic ion channel activity
Biological process: AV node cell to bundle of His cell communication by electrical coupling; cell communication involved in cardiac conduction; gap junction assembly; negative regulation of cell communication by electrical coupling involved in cardiac conduction; cell communication; cell-cell signaling; monoatomic ion transmembrane transport; negative regulation of cardiac conduction; negative regulation of heart rate; response to glucose; transmembrane transport
Cellular component: cell surface; connexin complex; plasma membrane; gap junction
Genetic constraint (gnomAD): Missense variants: 370 observed, 269.15 expected, observed/expected ratio (o/e) 1.37, 90% interval 1.26 to 1.5. Synonymous variants: 189 observed, 128.66 expected, observed/expected ratio (o/e) 1.47, 90% interval 1.3 to 1.66.
Homologues: Orthologues: chimpanzee GJD3 (99% identical), macaque GJD3 (97% identical), mouse Gjd3 (81% identical), rat Gjd3 (81% identical), rabbit GJD3 (81% identical), guinea pig GJD3 (57% identical), tropical clawed frog gjd3 (53% identical). Paralogues in human: GJA3 (36% identical), GJD2 (35% identical), GJA5 (34% identical), GJA8 (34% identical), GJC2 (34% identical), GJC1 (33% identical), GJA4 (33% identical), GJA1 (32% identical), GJA10 (30% identical), GJD4 (30% identical), GJA9 (30% identical), GJB1 (30% identical), and 8 more.
Diseases named in the same sentence as GJD3 in open-access papers:
GJD3 is named in the same sentence as 12 diseases in open-access papers, as found by Europe PMC text mining. Sharing a sentence is not in itself a finding about the gene and the disease. The quoted sentences say what the papers report.
atrial fibrillation (1 paper, 2022). A disorder characterized by an electrocardiographic finding of a supraventricular arrhythmia characterized by the replacement of consistent P waves by rapid oscillations or fibrillatory waves that vary in size, shape and timing and are accompanied by an irregular ventricular response. "ZFHX3 was identified as a crucial risk factor for atrial fibrillation, SYNE2 contributed to cardiac arrhythmia, and GJD3 caused abnormal atrioventricular node conduction." (PMID 35924220, 2022).
breast carcinoma (1 paper, 2021). "SPOCK2 and GJD3 mRNA overexpression were also found to be associated with cerebral metastasis in an external online database consisting of 204 primary breast cancers." (PMID 34203581, 2021). "This is further supported by the significantly overexpressed GJD3 mRNA levels in the fresh-frozen breast cancer samples that metastasize to the brain in the independent online cohort of 204 primary breast cancers." (PMID 34203581, 2021). "The role of GJD3 expression in the formation of cerebral seeding of ER- breast cancer requires, at this point, further ratification." (PMID 34203581, 2021). "In the current study, we found that the expression of BOC, SPOCK2, and GJD3 is upregulated in the ER- primary breast cancer samples of patients who developed brain metastases." (PMID 34203581, 2021). "Further analysis on the GJD3 protein status in 30 additional breast cancer samples showed a higher trend of GJD3 protein overexpression in the BM+ group." (PMID 34203581, 2021). "Three genes BOC, SPOCK2, and GJD3 were overexpressed in the group of primary breast cancers which developed brain metastasis." (PMID 34203581, 2021). "GJD3 was never before associated with breast cancer and it was believed that ancient connexins (groups IV and V) are not expressed in cancers in the first place." (PMID 34203581, 2021). "Nevertheless, the overexpression of GJD3 mRNA in primary breast cancers that developed brain metastasis was successfully confirmed in a publicly available online dataset of 204 primary breast cancers, when considering only breast cancers which metastasized exclusively to the brain (p = 0.0149)." (PMID 34203581, 2021).
Meniere disease (1 paper, 2024). A disease of the inner ear (labyrinth) that is characterized by fluctuating sensorineural hearing loss; tinnitus; episodic vertigo; and aural fullness. "Recently, it was revealed that familial Meniere’s disease affects both cochlear and vestibular organs through the enriched genetic burden of rare variants in OTOG and GJD3." (PMID 38610765, 2024).
Varicose veins (1 paper, 2023). Enlarged and tortuous veins. "A genome-wide association study in a Finnish cohort identifies several new loci associated with varicose veins, including the connexin gene family member, GJD3, as a future druggable target." (PMID 36653477, 2023). "A low-frequency missense variant in GJD3 (p.Pro59Thr) is exclusively associated with a lower risk for varicose veins (OR = 0.62 [0.55–0.70], P = 1.0 × 10−14) in a phenome-wide scan of the FinnGen data." (PMID 36653477, 2023).
GJD3 also shares sentences with these, for which no sentence is quoted: Tumor (2 papers); airway allergy (1); Allergy (1); breast tumors (1); cancer (1); cardiac arrhythmia (1); cardiac failure (1); leukemia (1).